AQP9 (aquaporin 9)
Description:
Aquaglyceroporins form homotetrameric transmembrane channels, with each monomer independently mediating glycerol and water transport across the plasma membrane along their osmotic gradient. AQP9 is the primary route for glycerol uptake in hepatocytes, supporting hepatic gluconeogenesis (By similarity). It exhibits broad specificity and may transport various small, non-charged solutes, including carbamides, polyols, purines, and pyrimidines. AQP9 may also facilitate hepatic urea extrusion. Due to its permeability to lactate, AQP9 might participate in the astrocyte-to-neuron lactate shuttle, supplying neurons with energy. Additionally, AQP9 is permeable to arsenite, contributing to arsenic excretion by the liver and providing partial protection against arsenic toxicity. It is also permeable to H2O2 in vivo. Could also be permeable to ammonium (By similarity).
Synonyms: AQP-9; SSC1; HsT17287; T17287
Tractability: Antibody: UniProt places it where antibodies can reach, with high confidence; its Gene Ontology location is reachable by antibodies, with high confidence; UniProt predicts a signal peptide or a membrane-spanning region. PROTAC: its protein half-life has been measured.
Gene: Protein-coding gene on chromosome 15 (58,138,169 to 58,185,914, forward strand). Ensembl gene ENSG00000103569.
Subcellular location: Cell membrane; Basolateral cell membrane
Subcellular location (Human Protein Atlas): Mid piece
Pathways (Reactome):
Transport of small molecules: Passive transport by Aquaporins; Transport of glycerol from adipocytes to the liver by Aquaporins
Gene Ontology:
Molecular function: channel activity; glycerol channel activity; hydrogen peroxide channel activity; protein binding; urea channel activity; water channel activity; purine nucleobase transmembrane transporter activity; pyrimidine nucleobase transmembrane transporter activity; urea transmembrane transporter activity
Biological process: cellular response to cAMP; glycerol transmembrane transport; urea transmembrane transport; water transport; amine transport; detoxification of arsenic-containing substance; purine nucleobase transport; pyrimidine nucleobase transport; hydrogen peroxide transmembrane transport; purine nucleobase transmembrane transport; pyrimidine-containing compound transmembrane transport; transmembrane transport
Cellular component: intracellular membrane-bounded organelle; plasma membrane; basolateral plasma membrane; membrane
Genetic constraint (gnomAD): Loss-of-function variants: 20 observed, 25.06 expected, observed/expected ratio (o/e) 0.8, 90% interval 0.56 to 1.16. The upper end of that interval is the gene's LOEUF score, 1.16, which puts it in group 5 of 6, group 1 being the genes least tolerant of losing a copy. Missense variants: 397 observed, 360.58 expected, observed/expected ratio (o/e) 1.1, 90% interval 1.01 to 1.2. Synonymous variants: 148 observed, 132.68 expected, observed/expected ratio (o/e) 1.12, 90% interval 0.98 to 1.28.
Homologues: Orthologues: chimpanzee AQP9 (99% identical), macaque AQP9 (96% identical), dog AQP9 (91% identical), rabbit AQP9 (85% identical), pig AQP9 (83% identical), guinea pig AQP9 (81% identical), mouse Aqp9 (76% identical), rat Aqp9 (76% identical), tropical clawed frog aqp9 (59% identical), zebrafish aqp10a (41% identical), zebrafish aqp10b (35% identical), Drosophila melanogaster Drip (23% identical), and 4 more. Paralogues in human: AQP10 (47% identical), AQP3 (46% identical), AQP7 (40% identical), AQP7B (37% identical), AQP2 (26% identical), AQP6 (26% identical), AQP5 (23% identical), MIP (23% identical), AQP4 (22% identical), AQP8 (22% identical), AQP1 (19% identical).
Diseases named in the same sentence as AQP9 in open-access papers:
AQP9 is named in the same sentence as 151 diseases in open-access papers, as found by Europe PMC text mining. Sharing a sentence is not in itself a finding about the gene and the disease. The quoted sentences say what the papers report.
hepatocellular carcinoma (32 papers, 2013 to 2025). A malignant tumor that arises from hepatocytes. "AQP9 is associated with ovarian cancer and hepatocellular carcinoma, in addition to inflammatory diseases such as rheumatoid arthritis and, more recently, endometriosis." (PMID 31533210, 2019). "In hepatocellular carcinoma decreased AQP9 expression has been associated with apoptosis resistance, invasion and epithelial-to-mesenchymal transition." (PMID 30042691, 2018). "What we extended further is that AQP9 overexpression in a human hepatoma cell line inhibited cell growth by causing cell cycle arrest at G1 phase and apoptosis." (PMID 27329843, 2016). "Additionally, AQP7 and AQP9 are overexpressed in malignant ovarian tumor cells compared to benign tumors or normal tissue and deficiently expressed in hepatocellular carcinoma associated with tumor aggressiveness." (PMID 39125952, 2024). "It was demonstrated that AQP9 may be an unique therapeutic or diagnostic target for hepatocellular cancer." (PMID 38336645, 2024). "Curiously, in hepatocellular carcinoma, AQP9 seems to promote the inhibition of tumor growth and metastasis via the Wnt/β-catenin pathway, standing as a promising therapeutic target for the treatment of this type of cancer." (PMID 40305202, 2025). "Conversely, AQP9 is found downregulated in hepatocellular carcinoma, and its overexpression prevents growth and EMT, thereby reducing hepatic cancer invasion and metastasis." (PMID 40305202, 2025). "Underexpression of AQPs for AQP8 has been observed in colorectal cancer, AQP8 and AQP9 in hepatocellular carcinoma, AQP4 in pleural mesothelioma, and AQP1 in cervical cancer." (PMID 40100646, 2025). "Using a rat hepatoma cell line, AQP9 showed a role in the lipid-lowering activity of silybin, a nutraceutical phytocompound, through modulation of the autophagic process and lipid droplet composition." (PMID 39596202, 2024). "It has been reported in the literature that the migration ability of hepatocellular carcinoma HepG2 cells is related to AQP9 expression, and the higher the AQP9 expression, the more invasive the hepatocellular carcinoma cells." (PMID 39048663, 2024). "The mechanism by which AQP9 promotes the migration of hepatocellular carcinoma cells is currently unclear." (PMID 39048663, 2024). "For hepatocellular carcinoma, AQP9 suppresses hepatocellular carcinoma cell growth and metastasis via distinct pathways, including HIF-1α, PI3k/Akt, Wnt/β-catenin, and FOXO1." (PMID 35972604, 2022). "Another experiment in a rat hepatocellular carcinoma model found that the expression of AQP9 was present at a low level before tumorigenesis, while it was significantly increased in the early stage of hepatocellular carcinoma." (PMID 35972604, 2022). "AQP9 expression was markedly down-regulated in hepatocellular carcinoma and was correlated to tumor size and number, TNM stage, five-year survival rate and metastases." (PMID 35477402, 2022). "In hepatocellular carcinoma cells, AQP9 overexpression, accompanied by reduced Wnt/β-catenin signaling and EMT-related molecules, inhibited proliferation, migration, and invasion." (PMID 35163313, 2022). "A recent study reported the ability of HTS13286 to prevent LPS-induced systemic inflammation via AQP9 blockage in rat hepatoma cells." (PMID 35187089, 2022). "AQP9 is elevated in astrocytic brain tumors, prostate, breast, colorectal, and gastric cancers, and decreased in lung cancer and hepatocellular carcinoma cells." (PMID 35163313, 2022). "AQP9 over-expression was shown to suppress the invasion of hepatoma cell by inhibiting EMT and to inhibit the growth of subcutaneously xenografted liver tumors in nude mice." (PMID 34830779, 2021). "AQP9 is downregulated in hepatocellular carcinoma but is elevated in many other cancers, including clear cell renal cell carcinoma, which suggests that it plays a complex role in cancer development." (PMID 33564686, 2021).
hepatocellular carcinoma (continued). "The contribution of AQP9 to the Plasmodium liver stage of P. falciparum, P. yoelii and P. berghei was investigated using primary human hepatocytes, human hepatoma cells and primary murine hepatocytes." (PMID 34268141, 2021). "FaO cells, a rodent hepatoma cell line expressing AQP9, were utilized to further investigate these observations." (PMID 33670755, 2021). "Contrary to liver steatosis, a recent work using subcutaneously xenografted liver tumors in nude mice showed that hepatic AQP9 overexpression inhibit hepatocellular carcinoma by upregulating forkhead-box protein O1 (FOXO1) expression." (PMID 30042691, 2018). "AQP9 is a potential target for hepatocellular carcinoma due to its decreased expression, which reduces apoptotic stimulation." (PMID 30555637, 2018). "AQP9 overexpression in SMMC7721 human hepatoma cell line inhibits cell colony formation and xenograft liver tumor growth." (PMID 27329843, 2016). "We found that AQP9 mRNA and protein levels were reduced in human hepatocellular cancer compared to the para-tumor normal liver tissues." (PMID 27329843, 2016). "In conclusion, we demonstrated that AQP9 mRNA and protein levels are reduced in human hepatocellular cancer compared to the para-tumor normal liver tissues." (PMID 27329843, 2016). "In HepG2 cells, a human hepatoma cell line, AQP9 was found to be up-regulated by insulin through the phosphatidylinositol 3-kinase/protein kinase B/mammalian target of rapamycin (PI3K/Akt/mTOR) signaling cascade." (PMID 27409609, 2016). "Up-regulation has been described for AQP9 in cultured human hepatoma cells treated with oleic acid, a compound with steatogenic effect." (PMID 24205128, 2013). "Interestingly, a study in hepatocellular carcinoma reported that AQP9 negatively impacts cell invasion by preventing the epithelial-mesenchymal transition." (PMID 39125952, 2024). "In hepatocellular carcinoma, decreased AQP9 expressions may suggest resistance to apoptotic stimuli." (PMID 38336645, 2024). "AQP9 expression was negatively mediated in HCCs and was mostly found in non-tumorigenic liver tissue Reduced AQP9 expression in HCCs can improve the sensitivity to apoptotic stimuli in hepatocellular carcinoma cells." (PMID 38336645, 2024). "AQP9 was reported to be most strongly expressed in cancers, including hepatocellular carcinoma." (PMID 36983834, 2023). "However, AQP9 protein expression was upregulated after treatment with oleic acid and Wy14643 in cultured human hepatoma cells." (PMID 35187089, 2022). "It is reasonable that AQP9 promotes cancer except for hepatocellular carcinoma." (PMID 35972604, 2022). "We focused our functional studies on AQP9, a membrane protein already suspected to be involved in the virulence of the rodent parasite P. berghei and whose gene expression was one of those most downregulated in hepatoma cells." (PMID 34268141, 2021). "Novel strategies based on clinically feasible approaches may be developed to restore AQP9 expression for the prevention and treatment of hepatocellular carcinoma." (PMID 30042691, 2018). "Decreased AQP9 expression was shown in hepatocellular carcinoma." (PMID 30042691, 2018). "Decreased AQP9 expression may indicate resistance to apoptotic stimulation in hepatocellular carcinoma." (PMID 30555637, 2018). "However, AQP9 has been found to be down-regulated in hepatocellular carcinoma and its over-expression suppresses hepatoma cell invasion through inhibiting epithelial-to-mesenchymal transition." (PMID 28415592, 2017). "Human hepatoma cell line SMMC7721 expressed low basal levels of AQP9." (PMID 27329843, 2016). "AQP9 was reported to be involved in the hepatocellular carcinoma." (PMID 27409609, 2016). "When AQP9 was overexpressed in SMMC7721 human hepatoma cell line, cell colony formation was reduced due to cell cycle arrest at G1 phase and increased apoptosis, which was linked to reduced PI3K and P-Akt levels and increased forkhead box protein O1 (FOXO1) levels." (PMID 27329843, 2016).
hepatocellular carcinoma (continued). "Importantly, the effects of Aqp9 deletion on NO and O2− production at the whole organism level could be confirmed in FaO rodent hepatoma cells." (PMID 33670755, 2021). "Conversely, AQP9, the most representative AQP in the liver, is downregulated in hepatocellular carcinoma and its overexpression suppresses hepatoma cell invasion via the epithelial–mesenchymal transition inhibition." (PMID 40305202, 2025). "A subsequent study showed that the inhibition of AQP9 with the specific and potent blocker RG100204 abolishes the LPS-induced increase in NO and O2− in FaO cells, a rat hepatoma cell line." (PMID 39596202, 2024). "However, the expression of AQP9 is downregulated in hepatocellular carcinoma (HCC) and the 5-year survival rate was significantly lower in patients with HCC and lower AQP9 expression than in patients with higher AQP9 expression." (PMID 38136293, 2023). "In addition, AQP9 overexpression prevented cell invasion, proliferation, and migration in vitro and tumor growth in vivo, suggesting direct involvement of AQP9 in the settings of hepatocellular carcinoma development by influencing epithelial-to-mesenchymal transition." (PMID 35883453, 2022). "In vitro, RG100204 blocked mouse AQP9 H2O2 permeability in an ectopic CHO cell expression system and abolished the LPS induced increase in superoxide anion and nitric oxide in FaO hepatoma cells." (PMID 35774785, 2022). "Here, through differential transcriptomic analysis of human hepatocytes and hepatoma HepG2-CD81 cells, the transmembrane protein Aquaporin-9 (AQP9) was found to be among the most downregulated genes in hepatoma cells." (PMID 34268141, 2021). "Aquaglyceroporin 9 (AQP9) is considered to be involved in numerous types of carcinogenic processes, particularly in liver carcinoma." (PMID 24959239, 2014). "Similarly, treatment of the same rodent hepatoma cell line with HTS13268, a blocker of the passage of glycerol and urea through AQP9, prevented the LPS-induced secretion of inflammatory cytokines." (PMID 39768394, 2024). "AQP9 expression is significantly decreased in the human hepatocellular carcinoma when compared with the non-tumourigenic liver, which leads to increased resistance to apoptosis." (PMID 24959239, 2014). "In hepatocellular carcinoma (HCC), AQP3 was upregulated, and AQP7 and AQP9 were downregulated, being significantly associated with the aggressive features of HCC." (PMID 35187089, 2022). "Improper AQP9 expression promotes chronic liver injury (CLI), which is a common disease resulting in hepatic steatosis, liver fibrosis, and eventually, if not treated, hepatocellular carcinoma (HCC)." (PMID 38674035, 2024).
Obesity (21 papers, 2012 to 2026). Accumulation of substantial excess body fat. "Like for AQP7, leptin has been shown to regulate hepatic AQP9 abundance, thus complicating the interpretation of the effect of obesity on AQP9 abundance in leptin deficient mice." (PMID 33193093, 2020). "AQP7 and AQP9 coordinated function is crucial for energy homeostasis and deregulation has been implicated in obesity and diabetes." (PMID 29977890, 2018). "In this sense, Aqp7 gene disruption leads to obesity, and Aqp9 deficiency is related to a defective hepatic glycerol metabolism in mice." (PMID 26594198, 2015). "Obesity has been associated with an increased gene and protein expression of AQP9 in human visceral fat." (PMID 24205128, 2013). "Evidence shows that aquaporin 9 (AQP9) could be implicated in adipose lipolysis during obesity conditions because lean subjects have decreased AQP9 expression in contrast to obese patients." (PMID 36432612, 2022). "The increased expression of AQP9 in subcutaneous adipose tissue was associated with human obesity." (PMID 31159441, 2019). "Taking this into account, AQP9 may play a crucial role in the success of spermatogenesis, particularly in pathological conditions associated with increased plasma glycerol levels (e.g., obesity, diabetes mellitus)." (PMID 27409609, 2016). "Reduced levels of AQP9 occurred in hepatocytes of murine models of obesity and subjects with obesity with type 2 diabetes where a significant reduction in liver glycerol permeability was also found." (PMID 39596202, 2024). "Both murine models of obesity and patients with obesity and type 2 diabetes have reduced levels of hepatic AQP9 accompanied by a decrease in liver glycerol permeability." (PMID 37630841, 2023). "Reduction in AQP9 levels and liver glycerol permeability were seen in hepatocytes of murine models of obesity and subjects with obesity with type 2 diabetes." (PMID 37681902, 2023). "It has been reported that adipose Aqp7 and Aqp9 gene expression was increased by diet-induced obesity in mice." (PMID 34360801, 2021). "The coordination and regulation of AQP7 and AQP9 play an important role in the control of obesity and hepatic steatosis." (PMID 31275413, 2019). "The causes for this sex-based difference in obesity-associated glycerol levels are not clear; however, it could relate to differences in the expression of adipose tissue AQP7 and hepatic AQP9, as shown in several mouse models of obesity." (PMID 40927981, 2026). "However, further studies are needed to confirm that the coordinated upregulation of AQP7 and AQP9 in relation to obesity also occurs at the protein level." (PMID 33193093, 2020). "AQP3 and AQP7 may facilitate glycerol efflux from adipose tissue while reducing the glycerol influx into hepatocytes via AQP9 to prevent the excessive lipid accumulation and the subsequent aggravation of hyperglycemia in human obesity." (PMID 31275413, 2019). "Selective modulation of AQP7 and AQP9 may constitute a promising approach for controlling obesity and metabolic-related disorders." (PMID 29977890, 2018). "In addition, obesity has been associated with increased AQP3 and AQP9 expression and decreased AQP7 expression in human subcutaneous adipose tissue." (PMID 29186031, 2017). "Interestingly, in human subcutaneous adipose tissue, obesity is associated with increased AQP3 and AQP9 expression and decreased AQP7 expression." (PMID 29186031, 2017). "Furthermore, shRNA-mediated reduction of Aqp9 expression reduces liver triacylglycerol (TAG) accumulation in a diet-induced rat model of obesity." (PMID 26416971, 2015). "Chronic leptin administration in male leptin-deficient ob/ob mice down-regulated adipose AQP3 and AQP7 at the same time as it upregulated hepatic AQP9 in parallel with the improvement of obesity and hepatosteatosis observed in this genetically obese animal model." (PMID 26594198, 2015).
Obesity (continued). "The opposite is true in liver, suggesting that reduction in glycerol influx in hepatocytes via AQP9 could prevent excessive lipid accumulation and may reduce hyperglycaemia in obesity." (PMID 22916037, 2012). "In different mouse models of obesity, a coordinated upregulation of AQP7 and AQP9 mRNA has been reported in male mice." (PMID 33193093, 2020). "In the present study, we aim to investigate whether HFD-induced obesity in mice results in a coordinated upregulation of AQP7 and AQP9 protein in WAT and the liver and whether the effect of HFD on glycerol metabolism is sex-specific." (PMID 33193093, 2020). "A role for AQP9 in regulating hepatic TAG synthesis in NAFLD was suggested when it was shown that both liver AQP9 and hepatocyte glycerol permeability are diminished in mouse models of NAFLD and in subjects with obesity, insulin-resistance and NAFLD." (PMID 27409609, 2016). "In this animal model of obesity Aqp9 gene deletion elevates plasma glucose and does not alleviate hepatosteatosis." (PMID 26416971, 2015). "Our results show that leptin restores the coordinated regulation of fat-specific AQP7 and liver-specific AQP9, a step which might prevent lipid overaccumulation in WAT and liver in obesity." (PMID 26159457, 2015). "Leptin deficiency was associated with obesity and NAFLD exhibiting an AQP3 and AQP7 increase in WAT, without changes in hepatic AQP9." (PMID 26159457, 2015).